EPCAM (epithelial cell adhesion molecule)
Diseases named in the same sentence as EPCAM in open-access papers (continued):
Sharing a sentence is not in itself a finding about the gene and the disease.
tumor (continued). "It has been suggested that the low prevalence of CTCs detected in patients with advanced NSCLC using the CellSearch system may be due to the loss of EpCAM expression, indicating that EpCAM-based CTC isolation methods cannot achieve stable and reproducible CTC recovery from all tumor types." (PMID 23840710, 2013). "Interestingly, the prognostic impact of EpCAM expression varies with tumor type." (PMID 23320927, 2013). "Similarly, primary tumor cells originating from the CD133+/EpCAM+ spheroid CSC-derived xenograft tumors exhibited a higher proliferative potential under the stem cell conditions compared to those from CD133−/EpCAM+ cell-derived xenograft tumors." (PMID 23826249, 2013). "Thus, a lower fraction of CD133+/EpCAM+ CSCs was observed in xenograft tumor tissues." (PMID 23826249, 2013). "L1CAM and EPCAM proteins could be useful markers to predict tumor progression and prognosis." (PMID 24422715, 2013). "The pan-tumor TAA, integrin α6 (CD49f), was validated to have an expression profile similar to EpCAM, demonstrating the potential of this technology to identify candidate tumor biomarkers that could be used to further refine the detection of malignant cells, including CTCs/DTCs." (PMID 23308131, 2013). "We chose EpCAM as a target moiety to deliver siRNA because this molecule is highly expressed in various epithelial cancers and is an ideal target as it is highly expressed in the apical surface of tumor cells while showing basolateral expression in normal cells." (PMID 23687439, 2013). "Flow cytometry for EpCAM as an indicator of tumor cells in these culture pairs found that the second cultures were significantly enriched for tumor cells (60-80% vs. 2-30%) yet this culture produces less DcR3 than the first adhesion culture with only a fraction the number of tumor cells." (PMID 22583667, 2012). "We next examined whether EpCAM or CD133 staining intensity correlated with tumor recurrence." (PMID 23216644, 2012). "The intention of these experiments was to test: a) whether EpCAM-antibody mediated tumor cell immobilization on the FSMW occurs under conditions similar to venous blood flow and b) whether non-malignant blood cells are interfering with the capture capability of the FSMW." (PMID 22825490, 2012). "In addition, the expression of EpCAM might be modulated during the process of epithelial-to-mesenchymal transition that is closely related to the initial steps of tumour cell dissemination, with the subsequent impact on CTC isolation." (PMID 22304365, 2012). "Thus, detection of EpCAM-positive tumour cells could signify the presence of cells with stem-like properties in BM, potentially contributing to the observed association with metastasis development and patient survival." (PMID 21448171, 2011). "Given the striking association between the ability of fibroblasts to secrete PGE2 in vitro and the ability to expand CD44+/CD24−/EpCAM+ cells and support tumor growth, we speculated that perhaps PGE2 signaling enhances the tumor promoting phenotypes of fibroblasts." (PMID 21957456, 2011). "As EpCAM is not tumour-specific, but rather is tumour-associated and also expressed on normal epithelial tissue, high affinity conventional mAbs may be disadvantageous, with therapeutic concentrations that cause severe adverse events." (PMID 17622246, 2007). "Indeed, there may be a golden window of opportunity when EpCAM expression increases to a point after which metastatic tumour cells reduce expression." (PMID 17325709, 2007).
tumor (continued). "Western blotting was additionally performed to assess cancer stemness in tumor tissues after DC101 treatment, revealing decreased expression of EpCAM." (PMID 41140754, 2026). "Eight genes exhibited greater than 340-fold increases in expression in tumor tissues (CLDN6, KLK7, WNT10A, MYBL2, MAL2, KRT7, PRSS8, EPCAM; Median (Range) of fold increase = 344 (261–7267))." (PMID 41465326, 2025). "To assess the fidelity of our patient-derived organoids, we compared the expression and spatial distribution of key tumor markers (EpCAM, PAX8, and CA125) between organoids and their original tumor tissues." (PMID 41009433, 2025). "FACS analysis confirmed the presence of tumour cells expressing both LY6D and EPCAM, thereby confirming the presence of this hybrid squamous-like state in primary human CRC samples." (PMID 40468074, 2025). "AFP correlates with several tumor target proteins for immunotherapy, including VEGFR and epithelial cell adhesion molecule (EpCAM)." (PMID 39714631, 2025). "BIN1 overexpression correlated with reduced expression of key stemness and EMT markers, including Myc, ALDH1, OCT4, EPCAM, KLF4, NANOG, SOX2, and decreased tumor sphere-formation capabilities, suggesting EMT inhibition." (PMID 40016843, 2025). "These conjugates exhibit potent binding and effectively inhibit the growth of tumor cells with high levels of both EpCAM and CLDN3, indicating their anti-tumor efficacy." (PMID 40057807, 2025). "For instance, in the comparison between PCa tumor and normal samples, DiCE identified 61 cancer fitness genes, including MYC, CCNA2, PLK1, PTTG1, EPCAM, and MTOR, that were overlooked by typical DEA but are well-documented contributors to PCa progression." (PMID 40626556, 2025). "In immunocompetent hosts, only a few tumor cells were detectable at the MRD stage, and a negligible fraction of these expressed epithelial markers such as EpCAM and E-cadherin." (PMID 40738896, 2025). "A previous study demonstrated that systemically infused murine EpCAM CAR-T cells accumulated in the critical organs and resulted in on-target, off-tumor toxicity." (PMID 41417221, 2025). "Conversely, tumors exhibiting a high EpCAM/CD44+ cellular profile maintained a differentiated phenotype, mirroring the morphological and phenotypic heterogeneity of the primary tumor mass." (PMID 40647400, 2025). "Our findings that detection of Ki67 and AnxA6 together with EpCAM for epithelial/proliferative cells and vimentin for mesenchymal-like/invasive cells can be used to identify these cell types in a typical TNBC tumor for rational treatment strategies." (PMID 41279138, 2025). "Immunohistochemistry analysis revealed that protein was mainly expressed in cytoplasm of tumor cells for CD44, CD90, and CD133, while EpCAM was mostly expressed in cell membrane." (PMID 40791212, 2025). "In the mIHC, the CCA, marked by CK19, EPCAM and CD44 was observed, further indicating an increase in the CCA and heightened tumor malignancy in DEN + MSCs group." (PMID 39674501, 2025). "We found that the EDEM3 expression in epithelial cells (marked by KRT18, EPCAM, KRT8) was significantly higher in tumour tissues with a large proportion of CAFs (marked by COL1A1, COL1A2, COL6A1, COL6A2) in the GSE188711 CRC dataset." (PMID 39754316, 2025). "The mIHC images revealed that marker genes of epithelial cells (EPCAM, DSP and TXNRD1) were highly expressed in tumor regions, especially in the metastasis-related regions." (PMID 39741182, 2025). "Our findings put forward a new viewpoint on the interactions between EpCAM and EGFR in the membranes of stem cells and even tumour cells and provide potential targets for the CTE therapy." (PMID 39939830, 2025). "The overexpression of miR-17-5p markedly elevates the expression of stem cell markers CD44 and EpCAM in MGC-803 gastric cancer cells, augments tumor spheroid forming capacity, and promotes cellular resistance to chemotherapeutic agents." (PMID 40710326, 2025).
tumor (continued). "Circulating tumor cell subsets expressing cancer stem cell markers (CD90, epithelial cell adhesion molecule; CD133, vimentin) were assessed using multiparametric flow cytometry and compared with alpha-fetoprotein and des-gamma-carboxy prothrombin." (PMID 40940925, 2025). "Conventional biomarkers, such as carcinoembryonic antigen (CEA), epithelial cell adhesion molecules (EPCAM), and EGFR, can be found in lung tissue, tumor-draining pulmonary blood, and bone marrow samples used for diagnosing NSCLC." (PMID 40176898, 2025). "Here, we generated a BsADC targeting EpCAM and CLDN3 to deliver potent toxin payload more precisely to the tumors and mitigate on-target off-tumor toxicity." (PMID 40057807, 2025). "The TAAs EpCAM, TROP2, and MUC1 showed the highest and most consistent expression across five PDAC cell lines and 14 primary tumor samples." (PMID 40358156, 2025). "PLGA nanoparticles help bypass these mechanisms by enhancing intracellular drug accumulation, enabling ligand-mediated active targeting (e.g., EpCAM, CD44), and triggered drug release within the tumor microenvironment." (PMID 41233827, 2025). "Immunohistochemistry (IHC) and immunofluorescence (IF) staining for cholangiocyte markers (EPCAM and CK7) confirmed strong expression in both PDOs and primary tumor tissues, indicating that PDOs retain key biological features of the original tumors." (PMID 41438056, 2025). "We further detected the protein expression levels of EPCAM and CLDN3 on these tumor cells by FACS, and the results were consistent with mRNA expression." (PMID 40057807, 2025). "This led to the development of a conditionally active biological (CAB) BsAb that binds to both EpCAM and CD3 in an acidic tumor environment but limits binding to EpCAM and CD3 in normal tissues." (PMID 40565299, 2025). "Some of them lack EpCAM expression, while others even co-express CD45, along with macrophage/myeloid and tumour markers." (PMID 39967663, 2025). "Numerous markers for CSCs have been proposed across various tumor types, and advancements have been made by targeting CSC surface markers such as CD44, CD133, and EpCAM." (PMID 41368628, 2025). "While EpCAM and Trop2 are relatively weak cell adhesion molecules compared to the classical junction proteins such as E-Cadherin, this may be an advantage for forming clusters with tumor-resident immune cells prior to invasion of the surrounding connective tissue." (PMID 40867346, 2025). "The tumour stemness‐related genes CD133, EpCAM, CD44, L1CAM, ROR1, CD371 and so forth are the main research targets." (PMID 40665579, 2025). "Next, we conducted qRT-PCR and WB experiments, which demonstrated positive correlations between levels of USP15 and those of molecules related to tumor stemness (CD133, EPCAM, SOX2, ALDH1 and OCT4)." (PMID 39794359, 2025). "Pharmacokinetic profiles of EpCAM X CLDN3 BsADC 3 and total antibody in non-tumor bearing mice were evaluated after single intravenous administration of BsADC 3 and the IgG-ADC at doses of 10 mg/kg." (PMID 40057807, 2025). "Of particular interest are PLGA NPs equipped with ligands like EpCAM, CD44, and CXCR4—that guide therapies directly to tumor sites, improving both selectivity and uptake by cancer cells." (PMID 41233827, 2025). "The approach preserves adhesion molecules intrinsic to tumor-cell membranes, such as ICAM-1 and EpCAM, thereby enabling selective recognition and binding to homologous tumor cells." (PMID 41209565, 2025). "Similarly, the low tumor cell isolation efficiency that was found here for immunomagnetic enrichment of tumor cells using EpCAM (MACS cell separation system, Miltenyi Biotec) may be the result of tumor cell aggregates clogging the MACS columns used with this technology." (PMID 40525275, 2025). "An anti-EpCAM × anti-CD3 bispecific antibody, M701, was constructed as a T-cell engager to eliminate tumor cells in the peritoneal cavity." (PMID 41275209, 2025).
tumor (continued). "We further explored how expression levels of EGFR, EpCAM, TF, and TROP2 varied with clinical parameters such as tumor stage, grade, age, HER2 expression, and Ki-67 proliferation index." (PMID 40806559, 2025). "As shown by flow cytometric analysis of EGFP signal in tumor-derived single cells, mRNA-EGFP was primarily expressed in CD45− cells, especially in CD45− EpCAM+ cells, which are likely 4T1 tumor cells." (PMID 40777396, 2025). "CSCs are partially defined by specific cell surface markers, including CD133, CD44, CD90, EpCAM, and ALDH; however, the variability of these markers across tumor types poses challenges for their use as universal therapeutic targets." (PMID 40868290, 2025). "Our study demonstrated that CEA, EpCAM, and c-MET are abundantly expressed in rectal cancer tumors, with nCRT exerting minimal impact on their expression in both tumor and adjacent normal tissues." (PMID 40563608, 2025). "These approaches merge IL-2 with antibodies directed at TAAs (e.g., EpCAM, GD2, CD20, and CEA) or tumor extracellular matrix (ECM) components, enabling selective delivery to the TME and local immune activation." (PMID 40508202, 2025). "In the IHC staining of tumor tissue, the CCA-positive area, marked by CK19, CK7, EPCAM, and CD44, in silent IGF2R-MSCs groups were lower than those in the MSCs group." (PMID 39674501, 2025). "On the other hand, in tumours like the MDA-MB-231 cell line, which exhibits high EGFR and low EpCAM expression, targeting EGFR for NIR-PIT would be more effective." (PMID 40792441, 2025). "Co-immunofluorescence staining for EPCAM and KRT5 in subcutaneous tumours demonstrated an apparent continuum of cell states." (PMID 40468074, 2025). "Its upregulation enhanced tumor growth, invasion, epithelial-mesenchymal transition, and stem-like characteristics by increasing key markers (CD44, EpCAM, SOX2, and Nanog)." (PMID 40290725, 2025). "We observed a statistically lower proportion of EpCAM and CD56 expression on tumor cells in patients with NSCLC than those with SCLC (respectively, 70.1 vs. 87.5%, p = 0.0004, and 60.4 vs. 88.5%, p = 0.0112)." (PMID 39941799, 2025). "Focusing on LUAD patients’ spatial transcriptomics data from SCAR, we utilized hematoxylin-eosin staining (HE) sections and the Epithelial cell adhesion molecule (EPCAM) cell marker to delineate fibroblast and tumor regions." (PMID 39962118, 2025). "Several other promising CAR T-cell tumor targets were identified, including alpha-fetoprotein (AFP), Epithelial cell adhesion molecule (EpCAM), Claudin18.2 (CLD18), CD133, and c-MET61." (PMID 40626281, 2025). "While markers such as CD133, EpCAM, and certain lncRNAs have been associated with liver TICs, their diagnostic accuracy remains constrained due to non-exclusive expression in other liver or tumor microenvironment cell types, which can lead to false positives or negatives." (PMID 40568600, 2025). "Among these, KRT14+ epithelial/tumor cells derived from tumor tissue significantly expressed unique BCC-related gene molecular markers, such as BCAM and EPCAM." (PMID 41383502, 2025). "Sequential tissue sections from biopsy samples were stained for CEA, EpCAM, c-MET, and EGFR, with tumor expression levels quantified using the H-score method." (PMID 40563608, 2025). "In contrast, bispecific CAR-T cells targeting both EpCAM and ICAM - 1 showed enhanced antitumor activity, with the ability to prevent resistance and reduce relapse driven by heterogeneous or EpCAM-negative tumor subpopulations." (PMID 40977703, 2025). "The canonical markers EPCAM and KRT19 identified tumor cells, while CD3D, CD2, PTPRC, CD14, AIF1, CD79A, and COL1A2 validated non-tumor cells." (PMID 39955556, 2025).
tumor (continued). "EpCAM plays a pivotal role in the progression, metastasis, and therapeutic resistance of OSCC by regulating the CSC properties and tumor microenvironment interactions." (PMID 39996844, 2025). "To spatially resolve tumor cell phenotypes, we performed an UMAP algorithm on EpCAM+CD90−CD140a−CD45−CD33−CD14− cells from both PF and tumor tissue." (PMID 40877861, 2025). "Next, we examined the location of the expression for two marker genes—EPCAM, which is a marker of malignant cells, and SFRP4, which is more highly expressed in the adjacent tumor microenvironment." (PMID 40954301, 2025). "No significant changes were observed in the expression levels of ALDH1 and EpCAM, other CSC markers, between treated and control tumor samples." (PMID 40371330, 2025). "Malignant epithelial cells expressed secretory markers including EPCAM, cytokeratins (KRT8/10/18), MUC16, the carrier of the CA125 tumor marker, and mesothelin (MSLN), an OC differentiation antigen." (PMID 40164596, 2025). "In a study, concentrations of circulating tumour-derived EVs expressing B7H3/CD276, Mucin-1 (MUC1), and EpCAM in DTC compared to HCs, all three are epithelial tumour markers known to be overexpressed in TC." (PMID 41193833, 2025). "To investigate the clinical relevance of EGFR, EpCAM, TF, and TROP2 expression, we stratified TNBC tissue samples by tumor stage (I–III), histological grade (G1–G3), and patient age and assessed marker distribution via mIF analysis." (PMID 40806559, 2025). "By pairing CD47 blockade with tumor-specific targets (e.g., CD20 or EpCAM), these agents achieve selective activity on malignant cells while sparing RBCs and other healthy tissues." (PMID 41179296, 2025). "The novel synthesis of doxorubicin hydrochloride (DOX·HCl) and siRNA-loaded polymer vesicles labeled with anti-EpCAM antibody demonstrated effective liver CSC killing and tumor growth inhibition with reduced toxicity to normal cells in vitro." (PMID 39996844, 2025). "EGFR-activity subtypes characterized by accumulating expression of AREG and concurrently reduced expression of epithelial marker EpCAM promote de-differentiation towards EMT, local invasion, tumor budding, and are correlated to worsened OS." (PMID 40121428, 2025). "For instance, in epithelial ovarian cancer, a positive correlation has been detected between EpCAM and EGFR expression in tumor tissues." (PMID 40699639, 2025). "By analyzing the spatial distribution of EPCAM expression, RAC1 expression, and B cell regions, we found that RAC1 is strongly co-localized with EPCAM and B cells are mainly distributed in non-tumor core regions and tumor margin areas." (PMID 39898257, 2025). "Early tumor shrinkage was accompanied by changes in CD90(+) and EpCAM(+) CTC counts, whereas AFP and DCP remained largely unchanged." (PMID 40940925, 2025). "For example, a bispecific antibody targeting EpCAM (a tumor antigen) and CD3 (a T - cell marker) has shown significant anti - tumor activity by recruiting T - cells to the tumor microenvironment and triggering their cytotoxic functions." (PMID 41030448, 2025). "First, we analyzed the distribution of tumor (EpCAM+) and immune (PTPRC/CD45+) cells within the tumor tissue, confirming that these 2 cell populations were largely nonoverlapping." (PMID 41376815, 2025). "OmniCAR employs a truncated SpyCatcher ectodomain paired with SpyTag-equipped antibodies or designed ankyrin repeat proteins (DARPins), demonstrating in vivo efficacy targeting CD20, Her2, EpCAM, or EGFR tumours." (PMID 41465327, 2025). "In line with this, we showed that IgA mAbs against EpCAM can activate neutrophils to lyse various PDAC cell lines and tumor cells, which can be augmented by addition of CD47 blockade." (PMID 40358156, 2025). "Flow cytometry and immunofluorescence assays revealed reduced expression of CRC-SC markers, such as CD44, EpCAM, and CD133, in tumor mass samples explanted from EM127-treated mice." (PMID 40588481, 2025).